RBBP8P1 (RBBP8 pseudogene 1)
Gene: Protein-coding gene on chromosome X (118,632,375 to 118,634,616, reverse strand). Ensembl gene ENSG00000230399.
Homologues: Orthologues: mouse Gm61610 (31% identical).